CLPTM1L (CLPTM1 like)
Diseases named in the same sentence as CLPTM1L in open-access papers (continued):
Sharing a sentence is not in itself a finding about the gene and the disease.
cleft palate (1 paper, 2011). Cleft palate is a fissure type embryopathy that affects the soft and hard palate to varying degrees. "The second gene in 5p15.33 is CLPTM1L, which is implicated in the susceptibility to cleft palate." (PMID 21966413, 2011).
colon cancer (1 paper, 2018). "In DLD1 colon cancer cells PLOD2 and CLPTM1L mRNA expression was downregulated after Evi/Wls silencing by shmirRNA." (PMID 29453334, 2018).
cutaneous melanoma (1 paper, 2017). A primary melanoma arising from atypical melanocytes in the skin. "Finally, we conducted an eQTL analysis on 333 cutaneous melanomas from The Cancer Genome Atlas and also showed a higher expression of CLPTM1L with the risk allele of rs465498." (PMID 28781888, 2017).
dependence (1 paper, 2014). "Among our four ‘control’ genes, gene variations in TERT (rs2736100 and rs2853676) and CLPTM1L (rs401681 and rs31489) have a significant direct association with lung ADC risk but not an indirect effect through nicotine dependence." (PMID 25233467, 2014).
endometrial tumours (1 paper, 2015). "Our analysis of microarray datasets suggested differences in CLPTM1L expression between endometrial tumour histological subtypes, and increased expression of both TERT and CLPTM1L between endometrial tumour and normal tissue." (PMID 25487306, 2015).
gastrointestinal stromal tumor (1 paper, 2015). "However, the contribution of polymorphisms in the TERT and CLPTM1L gene region to gastrointestinal stromal tumors (GISTs) risk is still unknown." (PMID 26372813, 2015).
metastatic cancers (1 paper, 2021). A carcinoma which has spread from the original site of growth to another anatomic site. "Recent research shows that the SNPs of CLPTM1L were associated with many human malignancies, especially in some highly aggressive and metastatic cancers." (PMID 34938740, 2021).
nasopharyngeal carcinoma (1 paper, 2025). A carcinoma arising from the nasopharyngeal epithelium. "CLPTM1L has been identified as a susceptibility gene associated with nasopharyngeal carcinoma (NPC) risk, but its biological function and underlying mechanisms remain unclear." (PMID 40550808, 2025).
neuroblastoma (1 paper, 2025). Neuroblastoma (NB) is the most common solid, extracranial childhood tumor. "Unique breakpoint sequences were identified in the TERT locus (chr5:1252600-1345000 encompassing the TERT and CLPTM1L genes; genome assembly GRCh37/hg19), the breakpoint region, according to Peifer and colleagues, in 64 neuroblastomas from 55 patients." (PMID 39760332, 2025).
non-Hodgkin lymphoma (1 paper, 2018). Distinct from Hodgkin lymphoma both morphologically and biologically, non-Hodgkin lymphoma (NHL) is characterized by the absence of Reed-Sternberg cells, can occur at any age, and usually presents as a localized or generalized lymphadenopathy associated with fever and weight loss. "Finally, we used a commercially available anti-CLPTM1L antibody to perform immunohistochemistry on human tonsil and on bone marrow from patients with either non-Hodgkin’s lymphoma (non-involved bone marrow) or MM." (PMID 30042348, 2018).
non-melanoma skin carcinoma (1 paper, 2021). "On top of 5p15.33 (the locus of CLPTM1L and TERT), prostate and non-melanoma skin cancer also share 6p22.1-p21.31 and 21q22.2-q22.3." (PMID 34290314, 2021).
ovarian cystadenocarcinoma (1 paper, 2021). An adenocarcinoma that arises from the ovary and is characterized by the presence of cystic structures. "Spheroid growth was also inhibited in a dose-dependent manner by 102-5 anti-CLPTM1L in cisplatin-resistant, stem-like cell lines HeyA8-CisR, OVCAR5-CisR (HGSOC), and PeO4 (ovarian cystadenocarcinoma)." (PMID 33654182, 2021).
ovarian serous adenocarcinoma (1 paper, 2021). An adenocarcinoma that arises from the ovary and is characterized by the presence of malignant epithelial cells that, in well differentiated tumors, resemble the epithelium of the fallopian tube or, in poorly differentiated tumors, show anaplastic features and marked nuclear atypia. "High expression of CLPTM1L is associated with poor outcome in ovarian serous adenocarcinoma." (PMID 33654182, 2021). "To determine the level of CLPTM1L protein expression in ovarian serous adenocarcinoma, we conducted immunohistochemistry on frozen histology sections of treatment-naïve tumors from 24 patients." (PMID 33654182, 2021). "Similarly, OVCAR4 human ovarian serous adenocarcinoma cells were sensitized to carboplatin by treatment with 102-5 anti-CLPTM1L." (PMID 33654182, 2021).
rhinitis (1 paper, 2025). An inflammation of the mucous membrane lining the nose, usually associated with nasal discharge. "This elevated expression pattern was also observed in NPC biopsy samples, where CLPTM1L levels were markedly higher than in control tissues from patients with rhinitis, as revealed by transcriptome analysis." (PMID 40550808, 2025).
squamous cell carcinoma (1 paper, 2012). A carcinoma arising from squamous epithelial cells. "The percentage of strong staining (++∼+++) of CLPTM1L expression in adenocarcinoma was higher than that in squamous-cell carcinoma (p = 0.000)." (PMID 23300716, 2012).
cancer (67 papers, 2010 to 2026). A tumor composed of atypical neoplastic, often pleomorphic cells that invade other tissues. "The genomic region 5p15.13 is known to harbour many cancer susceptibility variants with at least two possible candidate genes CLPTM1L and TERT." (PMID 40321259, 2025). "At least ten independent GWAS signals within the ~100 kb genomic region on chromosome 5p15.33 harboring TERT and CLPTM1L have been associated with cancer risk or protection." (PMID 39956830, 2025). "Genome-wide association studies (GWAS) have revealed a significant association between the CLPTM1L locus and cervical cancer risk in European women, and aberrant expression of CLPTM1L has been noted in various malignant tumors." (PMID 39346724, 2024). "Elevated CLPTM1L expression is associated with heightened cancer malignancy and resistance to anticancer drugs." (PMID 38254939, 2023). "CLPTM1L (Cleft Lip and Palate Transmembrane Protein 1-Like) has previously been implicated in tumorigenesis and drug resistance in cancer." (PMID 38254939, 2023). "Our findings imply that the association between the CLPTM1L gene and various types of cancer can be potentially attributed to one distinct signal." (PMID 34355204, 2021). "It is suggested that rs401681 confers cancer susceptibility by regulating CLPTM1L and TERT expression, both genes implicated in carcinogenesis." (PMID 33879152, 2021). "The genomic region on chromosome 5 at 5p15.33, harboring TERT and cleft lip and palate associated transmembrane 1-like protein (CLPTM1L) genes, has been reported to contain several independent cancer susceptibility loci." (PMID 32121056, 2020). "We conducted a comprehensive meta-analysis of all relevant articles to provide a systematic and cumulative assessment of the association of CLPTM1L rs402710 and rs401681 polymorphisms and overall cancer risk." (PMID 29254260, 2017). "Recently, a number of investigations have been conducted to study the potential influence of Telomerase reverse transcriptase (TERT) and cleft lip and palate transmembrane 1-like (CLPTM1L) gene variation on cancer susceptibility." (PMID 29254260, 2017). "The TERT and CLPTM1L gene have been identified to be associated with carcinogenesis of at least 15 distinct cancers." (PMID 26372813, 2015). "Recent studies have suggested polymorphisms in the TERT and CLPTM1L region are associated with carcinogenesis of many distinct cancer types, including gastrointestinal cancers." (PMID 26372813, 2015). "Previous studies reported that TERT gene and CLPTM1L gene associated to the risk of many type of cancers." (PMID 23738012, 2013). "CLPTM1L encodes cleft lip and palate transmembrane protein 1‐like and could increase susceptibility to various cancers." (PMID 39950845, 2025). "Notably, several cancer-associated genes are located within a 1 Mb proximity including CLPTM1L, TERT, BRD9, TRIP13, NKD2, LPCAT1, and IRX4." (PMID 40278994, 2025). "CLPTM1L encodes a putative oncogene that promotes cancer cell growth and resistance to apoptosis." (PMID 39956830, 2025). "Given the important biological function of the TERT and CLPTM1L genes, previous cancer fine-mapping efforts in this region, and the appearance of multiple association peaks for some of the cancers, it is plausible to assume that multiple variants in this region affect cancer risk independently." (PMID 34355204, 2021). "Although the function of this gene is largely unknown, high expression levels of CLPTM1L have been observed in many cancers, and it is linked with cisplatin-induced apoptosis." (PMID 30079703, 2019). "PLPP5, CLPTM1L and ITM2C are poorly characterized proteins, whose functions are unknown, although mutation in CLPTM1L has been associated with several human cancers (see Discussion)." (PMID 30042348, 2018).
cancer (continued). "Epidemiological studies have identified several genetic polymorphism loci associated with increased cancer risk on chromosome 5p15.33, which contains two key genes, CLPTM1L (cleft lip and palate transmembrane 1-like) and TERT (telomerase reverse transcriptase)." (PMID 27655710, 2016). "The CLPTM1L gene is upregulated in cisplatin-resistant cell lines, and is linked to cisplatin-induced apoptosis; furthermore, over-expression of CLPTM1L mRNA has been observed in many cancers." (PMID 25007268, 2014). "Recently, several genome-wide association studies (GWAS) reported that common polymorphisms of Telomerase reverse transcriptase-cleft lip and palate transmembrane 1 like, CLPTM1L (TERT-CLPTM1L), which is located at locus 5p15.33, were associated with the risk of many types of cancer." (PMID 25007268, 2014). "In addition, CLPTM1L is also an attractive cancer susceptibility gene as it encodes a transcript whose overexpression has been linked to cisplatinum resistance." (PMID 23738012, 2013). "Besides, a comprehensive research synopsis with systematic functional annotation had not been performed to evaluate the epidemiological evidence of genetic correlations between TERT and CLPTM1L genes and susceptibility to cancers or non-cancer disease until now." (PMID 35847915, 2022). "We highlight CLPTM1L, LAMC1, and BABAM1 here due to previously-reported pleiotropic associations across multiple cancers." (PMID 40775447, 2025). "At least ten independent pleiotropic multi-cancer GWAS signals within the ~100 kb genomic region on chromosome 5p15.33 harboring TERT and CLPTM1L have been associated with cancer risk or protection." (PMID 39802763, 2024). "While the VNTR polymorphism of TERT has been investigated in relation to cancer susceptibility, the VNTR polymorphism of CLPTM1L remains unexplored." (PMID 38254939, 2023). "Specifically, the 5p15.33 region, harboring the TERT and CLPTM1L genes, showed statistically significant local genetic correlations for multiple cancer pairs." (PMID 34355204, 2021). "CLPTM1L's previous association with multiple mucosal and HPV-driven cancers suggests a role in regulation of viral transmission across epithelial barriers." (PMID 33794208, 2021). "The role of plasma membrane or extracellular CLPTM1L in EMT in cancer is a provocative subject of further research." (PMID 33654182, 2021). "This suggests that blocking CLPTM1L can markedly affect radioresistant NSCLC cells, whereas it has a weak effect on other cancer cells or normal cells because of the low levels of CLPTM1L in these cells." (PMID 32943060, 2020). "It has been reported that CLPTM1L functions mostly in cell cytoplasm during promoting the growth of cancer cells." (PMID 32943060, 2020). "Although CLPTM1L shows a strong genetic association with the development of NSCLC and is closely related to drug resistance in cancer cells, the role of CLPTM1L in the response to radiotherapy in NSCLC cells remains undetermined." (PMID 32943060, 2020). "CLPTM1L shRNA treatment in combination with irradiation significantly inhibited cancer cell growth in NSCLC xenograft tumors in vivo." (PMID 32943060, 2020). "The knock-down of CLPTM1L with siRNA or targeting with an anti-CLPTM1L antibody increased the sensitivity of CLPTM1L overexpressing cancer cells to killing through genotoxic stress inducing agents." (PMID 30042348, 2018). "It is possible that the location of CLPTM1L is dependent on cell context or that aberrant localization is a result of the high levels of expression seen in the examined cancer cell lines." (PMID 30042348, 2018). "CLPTM1L, near the TERT gene, is located at chromosome 5p15.33 which is widely identified as a susceptibility region associated with several types of cancer." (PMID 29254260, 2017). "There was also significantly higher expression of CLPTM1L in the NPC tissues compared to that in the non-cancer nasopharyngeal tissues (P < 0.001)." (PMID 26621837, 2016).
cancer (continued). "In this study, we found that the expression of CLPTM1L was higher in the NPC tissues compared to the non-cancer nasopharyngeal tissues, suggesting that the CLPTM1Lhas been implicated in NPC carcinogenesis." (PMID 26621837, 2016). "CLPTM1L is frequently upregulated in cancer cells and shows preserved colocalization with the TERT locus for a shared synteny in many species." (PMID 27977688, 2016). "In summary, our findings regarding genetic variation in the TERT and CLPTM1L region and GIST risk add to the growing body of literature suggesting the importance of this genetic region to cancer development." (PMID 26372813, 2015). "The CLPTM1L was originally identified among the genes involved in resistance to the anticancer agent cisplatin in cancer cell lines." (PMID 25233467, 2014). "The CLPTM1L gene has been documented to be upregulated in cisplatin-resistant cell lines and linked with cisplatin-induced apoptosis, and over-expression of CLPTM1L mRNA have been observed in many cancers." (PMID 23226346, 2012). "Epidemiological evidence for associations between variants in the TERT and CLPTM1L gene with risk of cancer and non-cancerous diseases in additive model." (PMID 35847915, 2022). "In addition, a series of genetic variants in MICA, MICB, NFKBIL1, SLC6A3, CLPTM1L, and TERT have been found to be associated with the susceptibility and prognosis of different cancer types." (PMID 35003220, 2021). "Depletion of these markers of stemness and inhibition of tumor spheroid growth suggest that 102-5 anti-CLPTM1L may prevent survival of cancer stem cells or stemness-related programming." (PMID 33654182, 2021). "In addition, we also found that the expression of TERT and CLPTM1L was higher in the NPC tissues compared to the non-cancer nasopharyngeal tissues." (PMID 26621837, 2016). "One of the novel associations (rs13174814) maps to a second region in the TERT promoter and the other (rs62329728) is in the promoter region of CLPTM1L; neither are correlated with previously reported cancer-associated SNPs." (PMID 25487306, 2015). "In addition, CLPTM1L was shown to play an anti-apoptotic role by protecting cancer cells from genotoxic-stress induced DNA damage." (PMID 23752272, 2013). "Over-expression of CLPTM1L mRNA was discovered in many kinds of cancer." (PMID 23653681, 2013). "However, additional genes linked to cancer processes were found deregulated in this study including AHRR, C7, CLPTM1L, and MRPS30 involved in apoptosis, CDH6 in cell adhesion and CEP72 in the cell cycle." (PMID 22412903, 2012). "In non-cancerous lung tissue, strong transcriptional activity overlaps with three transcripts of CLPTM1L, whereas in lung tumor, it is largely confined to the prioritized isoform, suggesting that genetic regulation of the isoTWAS-prioritized isoform is potentially cancer-specific." (PMID 40775447, 2025). "Even though numerous genetic association studies investigate the association of variant in TERT and CLPTM1L regions and cancers or non-cancer disease susceptibility, the conclusions are not always consistent and the functional mechanisms remain unclear." (PMID 35847915, 2022). "CLPTM1L gene may be associated in apoptosis processes and high expressed in cisplatin-resistant cell lines, TERT gene produce catalytic subunit of telomerase, associated with telomere maintaining and usually active in cancer cells." (PMID 33879152, 2021). "Therefore, CLPTM1L inhibition may be an attractive approach to adjunctive and/or maintenance therapy in ovarian and other cancers." (PMID 33654182, 2021). "The reduction in cell viability induced by MIR494 has been observed in other cancer types; indeed, several MIR494 targets have been thus far identified which are associated with reduced cellular survival including IGF2, c-KIT, HOXA10, CLPTM1L, SCGN, CXCR4, and c-myc." (PMID 26794413, 2016).
cancer (continued). "Genes at two of these loci, HERC2/OCA2 and IRF4, are involved in pigmentation, while the third, CLPTM1L/TERT, is a known cancer driver." (PMID 40495383, 2025). "These included two novel regions at 2p23.3 (containing e.g. GPN1) and 9q34.12 (LAMC3), as well as two previously known cancer loci at 9p21.3 (CDKN2B-AS1) and 5p15.33 (CLPTM1L)." (PMID 40278994, 2025). "Leveraging GWAS summary statistics for fourteen cancers, we observed pairwise local genetic correlations in the 5p15.33 region, harboring the TERT and CLPTM1L genes." (PMID 34355204, 2021). "Immunohistochemical staining using specific antibodies to Clptm1L or TMEM207 revealed that 31 of 89 tissue specimens exhibited concomitant expression of Clptm1L and TMEM207 at the cancer invasion front." (PMID 35047994, 2021). "Interestingly, some novel BC related proteins (STEAP4, CLPTM1L, TMEM41A, DHCR24, etc.) were also discovered, which have been reported to be involved in other cancer types." (PMID 33842315, 2021). "In addition, we found that knockdown of EGFR and CLPTM1L expression significantly inhibited migration and invasion, whereas knockdown of ATP9B or PQLC1 significantly enhanced migration and invasion of cancer cells." (PMID 28548104, 2017). "Moreover, we found that knockdown of expression of CLPTM1L, ATP9B, PQLC1 as well as EGFR significantly inhibited cancer cell migration and invasion." (PMID 28548104, 2017). "We applied this methodology to our study of an intergenic GWAS susceptibility variant, and established a role for the regulatory element in driving TERT (but not CLPTM1L) gene expression across multiple cancer types." (PMID 28447668, 2017). "In these types of cancers, miR-494 functions its tumor suppressive effects, and inhibites cell proliferation, cell migration, and cell invasion and promoting apoptosis by regulating different oncogenes in different cancer cells, such as VEGF, CXCR4, CLPTM1L, HOXA10, and c-MYC." (PMID 26317788, 2015). "Overexpression of CLPTM1L mRNA has been observed in many cancer types including non-melanoma skin cancers." (PMID 25007268, 2014). "Cancer and reproductive disease add prominent non-MHC signals at TERT and CLPTM1L alongside pan-category genes such as MIS18BP1 and BIRC3." (PMID 41166152, 2026).